MAGEA8 (MAGE family member A8)
Description:
Not known, though may play a role in embryonal development and tumor transformation or aspects of tumor progression.
Synonyms: CT1.8; MAGE8; MGC2182
Tractability: PROTAC: ubiquitination databases record sites on it.
Gene: Protein-coding gene on chromosome X (149,881,141 to 149,885,835, forward strand). Ensembl gene ENSG00000156009.
Gene Ontology:
Molecular function: protein binding; histone deacetylase binding
Biological process: negative regulation of transcription by RNA polymerase II
Cellular component: nucleus
Homologues: Orthologues: chimpanzee MAGEA8 (99% identical), macaque MAGEA8 (91% identical), rat Magea13 (38% identical), mouse Magea13 (38% identical), zebrafish ndnl2 (23% identical), Drosophila melanogaster MAGE (18% identical). Paralogues in human: MAGEA4 (72% identical), MAGEA1 (67% identical), MAGEA9 (67% identical), MAGEA9B (67% identical), MAGEA12 (64% identical), MAGEA2 (63% identical), MAGEA2B (63% identical), MAGEA3 (63% identical), MAGEA6 (63% identical), MAGEA11 (61% identical), MAGEA10 (58% identical), MAGEB16 (46% identical), and 25 more.
Diseases named in the same sentence as MAGEA8 in open-access papers:
MAGEA8 is named in the same sentence as 16 diseases in open-access papers, as found by Europe PMC text mining. Sharing a sentence is not in itself a finding about the gene and the disease. The quoted sentences say what the papers report.
bladder cancer (1 paper, 2024). "Other MAGEA family members, including MAGEA1 and MAGEA8, exhibited lower expression in bladder cancer compared to normal bladder specimens." (PMID 38254738, 2024). "It was found that frequencies of genomic alterations among MAGEA family members in bladder cancer were MAGEA1 1.8%, MAGEA2 1.6%, MAGEA3 1.9%, MAGEA4 1.6%, MAGEA6 2.6%, MAGEA8 1.7%, MAGEA10 2%, MAGEA11, 2.1%, and MAGEA12 2.4%." (PMID 38254738, 2024).
ovarian carcinoma (1 paper, 2015). A malignant neoplasm originating from the surface ovarian epithelium. "MAGEA8 is a CT antigen whose expression in normal adult tissues is restricted to the testis and placenta; family members MAGEA3, MAGEA1 were also scored by immunotherapy experts (ranks 8 and 44 out of 75) and have been shown to be expressed in ovarian cancers." (PMID 26622942, 2015).
cancer (2 papers, 2011 to 2020). A tumor composed of atypical neoplastic, often pleomorphic cells that invade other tissues. "With the exception of MAGEA8, we found that all the MAGE-A genes, were exclusively expressed in the bone marrow, testis and in cancer tissue." (PMID 32760472, 2020).
MAGEA8 also shares sentences with these, for which no sentence is quoted: breast carcinoma (2 papers); colon cancer (1); colorectal carcinoma (1); embryonic tumors (1); glioblastoma (1); hepatocellular carcinoma (1); melanoma (1); neuroblastoma (1); osteosarcoma (1); rhabdomyosarcoma (1); sarcoma (1); transitional cell carcinoma of the bladder (1); tumour (1).